CD4 (CD4 molecule)
Diseases named in the same sentence as CD4 in open-access papers (continued):
Sharing a sentence is not in itself a finding about the gene and the disease.
tumor (continued). "The administration of autologous pDCs, activated and pulsed with tumor antigens (gp100, tyrosinase), induces a systemic type I IFN response accompanied by the migration of pDCs in draining lymph nodes and triggering of antigen-specific CD4 and CD8 T-cells in patients with metastatic melanoma." (PMID 37190135, 2023). "Lmo@RBC generated immunogenicity through activating CD8+ and CD4+ T cells and eliminated tumor cells via producing NADPH oxidase-mediated reactive oxygen species (ROS) while retaining the capability of living Lmo to colonize the anaerobic tumor microenvironment." (PMID 37896250, 2023). "While CD4+ T cells support and modulate immune responses through different T-helper (Th) and regulatory subtypes, CD8+ T cells eliminate cells that might threaten the organism, for example, virus-infected or tumor cells." (PMID 37893076, 2023). "Moreover, the immunogenic mutanome of non-synonymous cancer mutations was predominantly recognized through CD4+ T cells, but not CD8+ T cells, in three mouse tumor models." (PMID 38328405, 2023). "In addition, CDK1 might also play a role in regulating processes in the tumor microenvironment (TME), such as NK/T-cell activation and CD4-positive alpha beta T-cell proliferation." (PMID 36950551, 2023). "Consistent with this, we found that the Cltc CD4+ T cell epitope could be replaced by PADRE(X) when tethered to the CD8+ T cell minimal epitope (Mut_48.10) in a vaccine/PD-1 blockade therapeutic combination regimen and still result in complete tumor rejection." (PMID 37655661, 2023). "It has been reported that PD-1+ CD4+ tumor infiltrating lymphocytes (TILs) and CD8+ TILs had less proliferative capacity comparing to the PD-1- CD8+ or CD4+ TILs, suggesting that both CD8+ and CD4+ TILs are functionally anergic through activation of the PD-1/PD-L1 pathway." (PMID 36875956, 2023). "The pathogenesis of CIC is multifactorial and still partially unknown: anti-tumor activity that collaterally effects the colonic tissue and the upregulation of specific systemic inflammatory pathways (i.e., CD8+ cytotoxic and CD4+ T lymphocytes) are mainly involved." (PMID 37511260, 2023). "To explore this hypothesis, we performed scRNA-seq analyses of sorted CD11b+ Ly6G- tumour-infiltrating mononuclear phagocytes from mice treated with our CD4 ACT protocol and from non-treated controls." (PMID 37316667, 2023). "Some other factors must mediate tumor eradication when CD4+ T and CD8+ T cells were absent." (PMID 37407600, 2023). "Consequently, SLPs can activate also the CD4+ TH cell response, providing helper factors (interferon γ [IFN-γ], tumor necrosis factor α, IL-2), essential for sustaining the cytotoxic CD8+ T cell responses and inducing the immune-mediated tumor cell killing." (PMID 37654484, 2023). "Therefore, CD4+ helper T cells can have both positive and negative regulatory roles in the tumor immune cycle, depending on their subset and the context of the tumor microenvironment." (PMID 37345086, 2023). "In indirect approaches, CD4+ T cells indirectly regulate CD8+ T cell response by DCs, interact with B cells or macrophages to indirectly modulate humoral immunity or macrophage polarization, and inhibit tumor blood vessel formation to promote antitumor response." (PMID 37829505, 2023). "The efficacy of tumor immunotherapy is restricted by tumor cells evading host immune system surveillance and downregulating the function of immune cells, especially antitumor effector cells, including CD8+ T and CD4+ T cells, natural killer cells (NK), and dendritic cells (DCs)." (PMID 38292478, 2023). "Because we were unable to control for these confounders in our specimens, it is unclear how they may have impacted tumor and HLA-DRB1 fucosylation and CD4+ T cell biology and thus the strength of correlations between these markers and responsiveness to treatment." (PMID 36690875, 2023).
tumor (continued). "Therefore, we performed immunofluorescence staining with FITC-conjugated IL-11Rα-targeting peptides in combination with anti-CD4 or anti-CD8 antibodies, respectively, to reflect the co-localization of tumor-infiltrating T cells and tumor cells in the tumor tissues." (PMID 38067271, 2023). "Interestingly, T cells expressing FoxP3, a marker usually associated with a regulatory T cell phenotype (Treg) with inhibitory function on CD4+ T cells, were more abundant in GL261-CIITA tumors compared to GL261 parental tumor (FoxP3: 618 cells/mm2 in GL261-CIITA; 29 cells/mm2 in GL261)." (PMID 36993983, 2023). "Although the number of CD4+CD25+CD127lo cells in Ccl21a-KO dLNs was significantly lower than that of WT dLNs without tumors, the number increased more significantly in Ccl21a-KO dLNs (approximately 6-fold) compared with the WT dLNs (approximately 1.7-fold) as the tumor grew." (PMID 37664721, 2023). "In particular, most tumor neoantigens are recognized by CD4+ T cells and not CD8+ T cells." (PMID 36776837, 2023). "CD8+ TMs expressing CCL5 and GZMA, MAIT (mucosal‐associated invariant T) cells expressing TCF7 and PLAC8, and CD4+ TNs (Naïve T cells) expressing CCR7 appeared in paratumour tissues, while CD4+ISG+ T cells expressing ISG15/20 and CD8+ TNs expressing TCF7 only appeared in tumour tissues." (PMID 36855810, 2023). "The selectively released Bu also reduced the PD-L1 protein expression in tumor cells (both in vivo and in vitro) via enhanced adenosine 5′-monophosphate-activated protein kinase (AMPK) phosphorylation, resulting in significant increases of CD8+, CD4+, and CD3+ T-cell infiltration in vivo." (PMID 37047123, 2023). "Outcomes included immunohistochemistry of dendritic cells (DCs), M1 and M2 macrophages, T-helper cells (Th1) (CD4+), cytotoxic T- lymphocytes (CTL) (CD8+), T-regulator cells (T-reg) (FoxP3+) and Fas Ligand activated CTLs (Fas-L+) in the periablational rim and untreated index tumor." (PMID 37883367, 2023). "In addition, we validated model-predicted immune cell densities against results from a digital pathology analysis, which is a quantitative analysis of histological images that provides spatial densities of immune markers of interest, such as CD4, CD8, and FoxP3, in different tumor regions." (PMID 37291190, 2023). "Moreover, the analysis carried out on CD8+CD137+ and CD4+CD137+ T cells revealed that these cellular subsets, examined as single populations, do not seem to have a particular impact on the induction of an anti-tumour immune response." (PMID 37108276, 2023). "So, although inhibition of Glutaminolysis in tumor cells is effective, it has not completely cleared the tumor lesions, which may be related to the tendency of CD4+ T differentiation changes to Treg after Glutaminolysis inhibition." (PMID 37545506, 2023). "Radiation decreased the relative proportion of all CD4+ T cell subsets while increasing the overall T cell infiltration in the tumor, and this may explain, in part, the strong effect of radiation on TCR clonality, as CD8+ T cells were generally more clonal than CD4+ T cells." (PMID 37620372, 2023). "Indeed, a recent study showed that IL2 and BLIMP1 induced cytotoxic function in tumor-specific CD4 T cells, and that this occurred independent of TBET-mediated induction of a Th1 polarization state." (PMID 37654482, 2023). "CRT plus PD-1 blockade did not affect the levels of tumor CD4+ and tumor CD8+ T cells." (PMID 37275884, 2023). "Therefore, whilst direct recognition of MHC II+ tumour cells can mediate tumour rejection, it is not prerequisite for CD4+ T-cell involvement in the anticancer immune response." (PMID 37386922, 2023). "Therefore, our hypothesis was that CD8+ and CD4+ T cells enhanced anti-tumor immunity in the low TES group, but Tregs reduced anti-tumor immune responses in the high TES group." (PMID 37207222, 2023).
tumor (continued). "Hence the suggested role of CD4+ T-cells is to shape and improve the CD8+ T-cell response that is induced, though CD4+ T cells do not restrain the tumor growth as much as CD8+ T cells." (PMID 37244905, 2023). "CD4 + CD26high T cells did not require CD8 + CAR T cells for persistence in the tumor." (PMID 37475035, 2023). "Additionally, increased conventional CD4 T cells and CD8 T cells are recruited to the tumor sites with closer co-locations; meanwhile, immunosuppressive cells such as regulatory T cells, tumor-associated macrophages, and MDSCs gradually decrease due to chemotherapy." (PMID 37173915, 2023). "However, if CD4+ and CD8+ T cells were depleted in mice, the anti-tumor effect of PBT was lost." (PMID 38169949, 2023). "Peripherally, CD4 T cells can also secrete IL-2 and IFN-γ, which have been found to elicit M1 macrophages to inhibit tumor propagation via secretion of nitric oxide synthase (iNOS), reactive oxygen species (ROS), and IL-12, resulting in direct and indirect clearance of tumor cells." (PMID 37009485, 2023). "Therefore, we further examined CD4+ and CD8+ T cells in spleens from these 4T1 tumor–bearing mice." (PMID 37847562, 2023). "Given the increase in tumor antigen-specific CD8+ T cells driven by CTLA4i, together with the increased expression of PD1 by lung CD4+ and CD8+ T cells driven by anti-CD40 we reasoned that anti-PD1 could be necessary to sustain responses elicited by RT+CTLA4i+anti-CD40." (PMID 37620372, 2023). "Noteworthy, XRCC4 expression was significant positive correlated with infiltration levels of CD4+ T cells, CD8+ T cells, dendritic cells, macrophage, and neutrophil, which infiltrated in TME have been known as both anti- and pro-tumor properties promote immunosuppression in tumor immune escape." (PMID 36765282, 2023). "MHC-II+ NCI-H2444 and DAN-G tumor cells do not present KRASG12V-derived epitope to CD4+ T cells." (PMID 36512410, 2023). "These T cell populations were also significantly increased in both tumor infiltrating CD4 T cells and CD8 T cells, regardless of whether they were positive or negative for PD-1." (PMID 37033927, 2023). "Furthermore, the effect in vivo of genetically modified monocytes for the release of IFNα into a mammary immunocompetent cancer model demonstrated increased infiltration of myeloid CD4 + and CD8 + T cells in the tumor microenvironment (TME) and decreased tumor burden." (PMID 36854896, 2023). "CD45+CD4+CD25+FRδ+ cells (i.e., Tregs) specifically captured the Ral-S0456 in a manner that was readily competed with excess Ral-glucosamine, i.e. confirming that the tumor Tregs could indeed bind raltitrexed." (PMID 37928524, 2023). "We demonstrated the expression of the β3-AR protein in tumor-infiltrating CD4+ and CD8+, and then through selective β1-, β2-, and β3-ARs silencing, we corroborated the prominent role of the β3-AR subtype, located on lymphocytes, in controlling the IFN-γ-dependent PD-L1 expression on NB tumor cells." (PMID 36854895, 2023). "On day 15 of treatment, we observed a significant upregulation of tumour immunogenicity markers (MHCI and PD-L1), significant increase in the proportion of tumour-infiltrating CD8+ and CD4+/FOXP3- T effector cells as well as the production of IFNγ by CD4+ T cells." (PMID 37582853, 2023). "So, interaction between activated CD4+ T-cells and cDC1 in TME may initiate a positive loop between TME and tumor-draining lymph nodes with sustained cDC1 migration and recruitment of effector T-cells and anti-tumor immunity." (PMID 36639382, 2023). "Furthermore, we observed a twofold increase in the number of CD4+TRM cells and a sixfold increase in the number of CD8+TRM cells in the skin at the tumor rechallenge sites compared to the concurrent accumulation of many activated CD69+CD103-T cells into the skin prior to the rechallenge." (PMID 37407600, 2023).
tumor (continued). "To complement the multiplex IHC experiments showing enrichment of CD4+/FOXP3+ and CD8+/PD-1 T cells in HCC samples of patients affected by HIV, we performed an exploratory targeted transcriptomic analysis of a smaller subset of 48 patient samples with viable tumour tissue." (PMID 37274775, 2023). "Furthermore, anti-PD1 treatment did not increase effector CD107a+CD8+ or CD107a+CD4+ T cells which are crucial for effective tumor cell killing in the tumor microenvironment." (PMID 36068918, 2023). "Thus, TRP-1 CD4+ T cells can indirectly recognize and kill MHC-II-deficient tumour cells in the absence of CD8+ T cells." (PMID 37316667, 2023). "This tumour did not express CD4, CD21 or fascin and had only variable expression with CD68." (PMID 36344905, 2023). "Three cell types (activated NK cells, resting memory CD4+ T cells, and CD8+ T cells) were selected, and it was speculated that these TME-related cell types could protect the normal cells from the invasion of tumor cells." (PMID 36902617, 2023). "Tumor cell-released autophagosomes from mouse cancer cell lines were found to stimulate the development of splenic B cells into CD1d + CD5 + IL10+ Bregs, which could potently suppress CD8+ and CD4+ T cell actions in vitro and in vivo." (PMID 37189748, 2023). "Furthermore, the therapeutic effects found in this model were abolished upon the deletion of TLR-4, suggesting a role of the innate immune system in anti-tumor response, independent of CD4+ T cells." (PMID 36992219, 2023). "The observation that the Mut_48 peptide, containing both a CD4+ and CD8+ T cell epitope, was the most effective NeoAg against a tumor lacking MHC II prompted us to investigate the functional contribution made by Cltc-specific CD4+ T cells toward therapeutic vaccination." (PMID 37655661, 2023). "However, adoptive transfer of CD4+ cells from previously C. novyi-NT cured animals did not prevent tumor establishment." (PMID 37514190, 2023). "In addition, results revealed that the combination could significantly reduce the proportion of Tregs in CD4+ T cells and also increase the proportion of CD3+ T cells in splenic lymphocytes of tumor‐bearing mice." (PMID 36373232, 2023). "However, the anti-tumor cells’ activated CD4 and activated CD8 signatures displayed negative correlations with mesenchymal states." (PMID 37884639, 2023). "In addition, hyperthermia could induced maturation of DCs that subsequently secreted more TNF-α and IL-12p70, which in turn synergistically induced the activation and proliferation of CD4+ and CD8+T cells and enhanced the anti-tumor immune response." (PMID 37828458, 2023). "Moreover, IL-17A expressing cells were also CD4-positive in wild-type mice, whereas in IL-17-deficient mice, we did not detect CD4/IL-17A double-positive cells, although CD4-positive cells accumulated in tumor regions as they do in wild-type mice." (PMID 38062130, 2023). "Notably, CD4+ and CD8+ T cells (light blue and dark blue lines, respectively) are most abundant in the periphery and border, particularly in SR tumors, dropping in abundance in the tumor core, while macrophages dominate in all spatial categories (maroon line)." (PMID 37704631, 2023). "Furthermore, our flow cytometry analysis showed that there were more populations of infiltrating CD8+ T cells in the tumour tissues of KO mice than those in WT mice, but the population of infiltrating CD4+ T cells was not altered." (PMID 36419386, 2023). "Notably, tumor-reactive CD8+ T cells - inclusive of cytotoxic, terminally exhausted, and pre-exhausted cells - present a higher proportion of CD27+ cells in comparison to all CD4+ T cells, Th17 cells, and naïve T cells." (PMID 37545491, 2023). "Finally, the B16F10-OVA-elicited T cell activation in the lung-draining LNs was specific to CD8+ T cells, as there was no detectable difference in activated CD4+ T cell or CD4+ TEM frequencies within wild-type or E2-/- tumor-draining mediastinal LNs." (PMID 37426658, 2023).
tumor (continued). "To directly assess whether the observed antitumor effects were attributed to the generation of functional tumor antigen-specific CD8+ T cells, we next performed antibody-mediated depletion of either CD8+ or CD4+ T cells in B16-F10-bearing STINGgt/gt mice receiving the combination therapy." (PMID 36949064, 2023). "Importantly, the killing was completely abolished by blockade of HLA-II, but not HLA-I, demonstrating that CD4 CTL-mediated tumor killing requires HLA-II recognition." (PMID 37185301, 2023). "However, their tumor-killing ability is counteracted by various factors, such as indoleamine 2,3-dioxygenase (IDO), vascular endothelial growth factor (VEGF), interleukin 10 (IL-10), hypoxia, and CD4+ T-cell deprivation." (PMID 37275909, 2023). "In the analysis of the spleen, RT combined with anti‐PD‐1 significantly increased CD3+CD4+ T cells and CD3+CD8+ T cells with decreasing infiltration of MDSCs, which may be related to the best tumor control and the abscopal effects in the combination treatment group." (PMID 37206639, 2023). "PancVAX2-induced CD4+ T cells did not express the cytotoxic effector molecule GzmB, suggesting that the CD4+ T cells were not directly cytolytic, as has been reported preclinically and clinically in a subset of tumor-reactive T cells." (PMID 38063199, 2023). "In addition, both CD4+ and CD8+ T cells in rejecting tumors had higher HLA-DR and PD-1 expression than in concomitant spleens, indicating greater T-cell activation in the tumor infiltrate." (PMID 37087494, 2023). "In addition, CD4+ T cells were shown capable of eradicating tumour cells that do not express MHC-II by mobilizing myeloid cells, which are specialized to process and present peptide epitopes on their MHC-II molecules." (PMID 37316667, 2023). "Notably, CD4 + helper T cells have the ability to fully support the potential of CD8 + T cells in vivo, and support a lasting tumor-specific cytotoxic T cell response by guiding down-regulation of co-inhibitory receptors and enhancing CD8 + T cells' ability to infiltrate tumors." (PMID 37208656, 2023). "Therefore, we sought to investigate whether TAGAP could modulate CD4+ T cell activity, which would imply an important role of TAGAP in orchestrating anti-tumor immunity." (PMID 37744350, 2023). "Moreover, the population of CD4+ and effector CD8+ T cells increases and the expression of PD-1 decreases in TRM-exhausted lesions, which in turn impairs the survival and growth of early tumor cells." (PMID 37187731, 2023). "Thus, there might be differences in GPR15-dependent infiltration of effector CD4+ and CD8+ T cells depending on the tumor location and subsequent changes in the TME (subcutaneous versus colon)." (PMID 38074634, 2023). "CD4+ T cells play multifaceted roles in chronic infection and tumor: constituting both favorable and deleterious subsets, enhancing CD8+ T cell function, and responding to ICB,427,431 which highlights potential next-generation therapeutics of harnessing CD4+ T cell function." (PMID 37332039, 2023). "Moreover, the expression of functional molecule derived from CD4+ T cells or CD8+ T cells in GPR84−/− tumor-free mice was not different from that of WT mice." (PMID 37105980, 2023). "Our data suggest that CD4+ T cells contribute to better outcomes in patients with PDAC, which may be mediated through their direct cytotoxicity against tumor cells and action as helper cells to potentiate dendritic cells, resulting in enhanced CD8+ T cell responses." (PMID 37405518, 2023). "TRP-1 CD4+ T cells also locally clustered at the invasive margin of MHC-deficient HCmel12 Jak1-KO tumours, whereas Pmel-1 CD8+ T cells only infiltrated the invasive margin but not the tumour centre." (PMID 37316667, 2023). "Likewise, it has been suggested that changes in the percentage of peripheral CD4+ CD25+ Foxp3+ regulatory T cells, a cell subset in charge of maintaining immune tolerance in the tumor microenvironment, may be predictive of irAEs." (PMID 36900420, 2023).